EGFR (epidermal growth factor receptor)
Diseases named in the same sentence as EGFR in open-access papers (continued):
Sharing a sentence is not in itself a finding about the gene and the disease.
glioma (continued). "Additionally, we verified the association between EGFR coding variants and glioma subgroups based on histological characteristics and molecular properties by referring to previous studies." (PMID 36347915, 2022). "EGFR overexpression has been associated with decontrolled cell proliferation and inhibition of apoptosis, as well as with the establishment of malignancy by inducing the progression of low-grade to high-grade glioma." (PMID 35884571, 2022). "Thus, EGFR inhibitors were predicted to be potential pharmacological therapies for high-risk groups in patients with glioma." (PMID 36698888, 2022). "Furthermore, three haplotypes (frequency > 5%) were used for logistic regression analysis, which revealed that EGFR-ht3 (OR = 0.69, P = 0.01) was associated with a decreased risk of glioma." (PMID 36347915, 2022). "Gliomas barely express oncogenic Ras mutations, but they often have increased Ras activity due to a mutation or amplification of upstream positive regulators, such as EGFR and PDGFR." (PMID 35628161, 2022). "The mutation of the EGFR tyrosine kinase is the most common genetic lesion in gliomas." (PMID 36003330, 2022). "We found that EGFR amplification is a phenomenon of IDH wildtype TERT mutated high-grade gliomas." (PMID 35453544, 2022). "In addition, in the gene therapy study of Cas13a, the researchers induced EGFR overexpression by regulating the key oncogenic genes in glioma cells and caused the apoptosis of glioma cells." (PMID 36232699, 2022). "Future work should confirm the functional association between EGFR variants and glioma." (PMID 36347915, 2022). "This study explored the association of EGFR SNPs with the risk of glioma." (PMID 36347915, 2022). "This study provided the first evidence that potentially functional polymorphisms in the EGFR gene, especially rs2227983 (K521R) and rs1050171 (Q787Q), may contribute to glioma susceptibility in the Korean population." (PMID 36347915, 2022). "AKT1, MTOR, CCND1, and EGFR are closely associated with autophagy and apoptosis in glioma." (PMID 35140796, 2022). "PET imaging studying [11C]C-erlotinib in glioma xenografts showed specific binding of the radiopharmaceutical for activating mutations of the kinase domain but no specific binding for activating mutations of the extracellular domain of the EGFR." (PMID 34209513, 2021). "Moreover, in the MSKCC datasets, EGFR amplification was also associated with bad prognosis of glioma." (PMID 33959491, 2021). "Here, we revealed the co-occurrence of EGFR amplification and CDKN2A deletion in patients with glioma, suggesting that the poor drug response of EGFR inhibitors in glioma may be associated with CDKN2A deletion." (PMID 33959491, 2021). "The present study aimed to investigate the anti-tumor efficacy of AZD3759 against glioma and determine its underlying mechanism to provide more clinical evidence for the application of AZD3759 for the treatment of patients with glioma and EGFR-sensitive mutations in clinical settings." (PMID 34635007, 2021). "Some specific antigens may be found on the surface of glioma cells, for example, EGFR variant III (EGFRvIII)." (PMID 34356864, 2021). "Indeed, we found that EGFR mutations were more common in older low-grade glioma patients (OR = 1.0865, 95% CI = 1.0525–1.1258, adj." (PMID 33879792, 2021). "Most prominently deployed against CD19-expressing cells in haematological malignancies, where they have achieved remarkable clinical efficacy, the only current clinically relevant mutant antigen target for CAR-T cells is the exon 2-7 deletion vIII variant of EGFR, commonly expressed in glioma." (PMID 34439399, 2021).
glioma (continued). "Importantly for OPALS, in 2019, experimental work again indicating the association between EGFR and the MR showed that spironolactone decreases GB cell survival and sensitized glioma cells to the EGFR inhibitor osimertinib." (PMID 34068720, 2021). "EGFRvIII is the most common variant, leading to constitutively active EGFR signaling in glioma." (PMID 33790740, 2021). "The results of our study support a hypothesis that T. gondii is associated with higher glioma grade through EGFR pathway activation." (PMID 34827431, 2021). "EGFR also showed high heterogeneity for risk of all glioma and GBM subtype, indicating gene expression in certain tissues may affect risk differently—for EGFR these were the hippocampus, hypothalamus and substantia nigra." (PMID 33504897, 2021). "In addition, off-target inhibition of EGFR by ibrutinib also abrogates the pro-tumoral function of glioma-derived pericytes with EGFR mutations." (PMID 34778053, 2021). "For example, a malignant cell subpopulation dominating the metastatic stage was demonstrated to be a biomarker in lung cancer, while a tumor-associated microglia/macrophage-mediated EGFR/ERBB2 feedback-crosstalk signaling module was proven to outperform traditional gene biomarkers in glioma." (PMID 34108022, 2021). "Furthermore, TBR/ADC combination had a higher diagnostic accuracy than each single imaging method for high-grade and IDH1-, hTERT-, and EGFR-mutated gliomas." (PMID 34912706, 2021). "Indeed, IDH-wild type gliomas often amplify epidermal growth factor receptor (EGFR), gain of chromosome 7 and loss of chromosome 10 and telomerase reverse transcriptase (TERT) promoter mutations." (PMID 33669525, 2021). "In the present study, the anti-tumor efficacy of AZD3759 against glioma and its underlying mechanism was investigated to provide more clinical evidence for the application of AZD3759 for the treatment of patients with glioma and EGFR-sensitive mutations in the clinic." (PMID 34635007, 2021). "Moreover, consistent with our study, researchers identified that miR‐148a was an oncogenic gene associated with glioma survival and affected EGFR activation or regulated glioma growth by mediating HIF1α and Notch signalling." (PMID 32412186, 2020). "In the present review, the authors have summarized epidemiology and risk factors associated with GBM, RTKs, and their inhibitors of intracellular signaling pathways in glioma, the clinical profile of small molecule inhibitors (EGFR–TKIs) drugs, and the associated multiple failures/resistance." (PMID 33321953, 2020). "In addition, this mutation can hypermethylate and modify important glioma-related genes, such as EGFR and PDGFRA28,29." (PMID 33221817, 2020). "The finding of extensive cooperative mutations in mutant EGFR gliomas that can influence prognosis and drug treatment response highlights the importance of integrated genomic diagnosis for developing rational, personalized polytherapy strategies in patients to improve survival." (PMID 32727536, 2020).
glioma (continued). "In addition, EVs from the blood and cerebrospinal fluid (CSF) of glioma patients were found to contain transcripts and protein of the mutated epidermal growth factor receptor variant EGFRvIII as well as mutant IDH1 transcripts and DNA." (PMID 32178271, 2020). "The modification (deletion+insertion) at the N-ter of gD constitutes a platform for the generation of fully retargeted oHSVs, as was demonstrated by the engineering of different scFvs directed to EGFR (oHSV R-611), PSMA (oHSV R-593) and EGFRvIII, a glioma-specific variant of EGFR (oHSV R-613)." (PMID 33167582, 2020). "Moreover, it has been shown that enforced expression of miRNA-7 caused down-regulation of EGFR and enhanced sensitivity to radiotherapy in glioma cells." (PMID 32592373, 2020). "Overexpression of EGFR is associated with cancer (high-grade glioma)." (PMID 32326241, 2020). "Activating EGFR mutations are common in IDH1 wild-type gliomas." (PMID 32727536, 2020). "IDHwt GBM PDOXs retained common glioma mutations, including EGFR, MDM4, PTEN, PIK3CA, and PTCH1." (PMID 33009951, 2020). "We focused on TMEM167A, as we had previously linked this gene to EGFR regulation in gliomas." (PMID 31947645, 2020). "The Hallmark protein secretion pathway includes EGFR, which has a known association with glioma." (PMID 33081688, 2020). "We hypothesized that conditional genome-wide piggyBac mutagenesis in the presence of a strong initiating EGFR mutation may be a fruitful approach for mapping cooperative glioma driver landscapes in vivo." (PMID 32727536, 2020). "A loss of miR-1238 may sensitize resistant glioma cells by targeting CAV1/EGFR pathway and could be a potential therapeutic target." (PMID 32038644, 2019). "Therefore, we analyzed the RNA-sequencing data combined with clinical traits of patient from TCGA database to explore the immune related features of EGFR mutation in glioma, and a prospect on inferior overall survival in EGFR mutated gliomas was obtained." (PMID 31801484, 2019). "Since increased expression of EGFR in tumor tissues has been reported to be associated with the malignancy and poor prognosis of glioma 37, we tend to test if EGFR in serum EVs could also reflect the malignancy of glioma." (PMID 31410219, 2019). "Additionally, EGFR amplification has been appointed as one of the causes for the development of radio-resistance in gliomas." (PMID 31623593, 2019). "We found that EGFR+ EVs exhibited high sensitivity (86.96%) and specificity (83.7%) in identifying glioma patients with an area under the curve (AUC) of 0.900 (95% CI of 0.8064 ~ 0.9936, P <0.0001), indicating the high diagnostic value of EGFR+ EVs in detecting glioma." (PMID 31410219, 2019). "We hypothesize that EGFR mutation in glioma shares the similar characteristics in modifying immune microenvironment." (PMID 31801484, 2019). "Furthermore, microvesicles released from aggressive glioma cells transferred the oncogenic epidermal growth factor receptor (EGFR) to tumor cells causing a propagation of oncogenic activity." (PMID 29181712, 2019). "Alteration of immune microenvironment since the EGFR mutation might influence the survival of glioma." (PMID 31801484, 2019). "Indeed, there is preclinical evidence for the immunogenicity of a number of neo-epitopes arising from hallmark glioma mutations, including EGFRvIII (an intragenic deletion of exons 2–7 of the epidermal growth factor receptor), IDH1R132H and H3.3K27M 35–37." (PMID 31601888, 2019). "Consequently, in gliomas driven by EGFR, EGFR is intrinsically linked to the packaging and release of exosomes." (PMID 30925917, 2019). "Specifically, in human gliomas EGFR is not only overexpressed but also occurs in several mutations." (PMID 30587839, 2018).
glioma (continued). "However, a tumor specific mutation of EGFR, the EGFRvIII, which is most frequently seen in patients with glioma, has emerged as an ideal target for CAR T cell treatment." (PMID 30619286, 2018). "In addition, after a strict Bonferroni correction analysis was applied, the significance level of the association between EGFR tSNPs and risk of glioma was attenuated." (PMID 28938685, 2017). "The exact mechanism about how rs1468727 plays a key role in EGFR function, and why it plays a different role even contrast role in glioma risk in various ethnicities remain unclear." (PMID 29156842, 2017). "In addition, genome-wide association studies (GWAS) have also been performed and the results suggested that SNPs at two loci of EGFR gene (rs11979158 and rs2252586) were associated with glioma risk." (PMID 29156842, 2017). "Third, some other EGFR gene polymorphisms such as rs7809394, rs10225877 and rs917881 were not analyzed in our study, because only one study reported the relationships between these polymorphisms and glioma risk." (PMID 29156842, 2017). "Whether rs11979158 was correlated with glioma risk in Asian populations needs further investigation, knowing that different genetic backgrounds might have great impacts on the role of EGFR gene polymorphisms in glioma etiology." (PMID 29156842, 2017). "Gliomas express the wild-type or mutated forms of EGFR, including the GBM specific EGFRvIII." (PMID 27878374, 2017). "And several studies have demonstrated that certain genotypes of the EGFR gene may be related to glioma susceptibility, which indicated EGFR polymorphisms play an important role in the carcinogensis of glioma." (PMID 28938685, 2017). "Loss of PTEN, found in approximately 36% of gliomas, may result in dramatic upregulation of this pathway and be a major source of resistance to EGFR therapies." (PMID 28316990, 2017). "Our study is the first meta-analysis to determinate the roles of 11 SNPs of EGFR in etiology and risk of glioma, which could offer new insights into treatment with a target-oriented approach." (PMID 29156842, 2017). "In addition, the IDH1.R132H, GNAS.R201C, and EGFR.T790M mutations in Glioma, EGC, and NSCLC were the most significantly different point mutations (p = 0.00021, 0.00027 and 0.0011, respectively)." (PMID 29038591, 2017). "Different SNPs in EGFR gene might have different impact on the risk of glioma in various ethnicities." (PMID 29156842, 2017). "As this receptor complex induced activation of AKT signaling and increased glioma radioresistance, it was suggested that assessment of integrin-b1/EGFR association might be useful to predict radiotherapy outcome." (PMID 29246031, 2017). "Besides the allelic model analysis, we further performed genotypic model analysis to investigate the role of EGFR variants on glioma risk." (PMID 28938685, 2017). "As the biological characteristics may vary in different subtypes, whether EGFR gene polymorphisms play different roles in different subtypes of gliomas needs further investigation." (PMID 29156842, 2017). "These EGFR gene polymorphisms provide new insights in treating glioma." (PMID 29156842, 2017). "EGFR pathway may also be associated with epithelial-mesenchymal transition (EMT) in gliomas, which plays a key role in cancer invasion and metastasis." (PMID 29207533, 2017). "Upregulation of wild-type (wt) EGFR or expression of the EGFR variant III (EGFRvIII) have been associated in U87 glioma cells with promotion of γ-H2AX foci resolution, a surrogate for DSB repair, and with the nuclear accumulation of ATM, DNA-PKcs and RAD51, essential for the activity of NHEJ and HR." (PMID 28587121, 2017).
glioma (continued). "Taken together, our data demonstrate that TRIM24 recruits STAT3 to chromatin in EGFR-driven glioma cells, which is dependent on H3K23ac association, thus providing evidence that TRIM24 binds with EGFR-upregulated H3K23ac, and then recruits STAT3 and stabilizes its interaction with chromatin." (PMID 29129908, 2017). "In conclusion, different SNPs in EGFR gene might have different impacts on the risk of glioma in various ethnicities, which offers new insights into the treatment with a target-oriented approach." (PMID 29156842, 2017). "However gene amplification or expression of wild-type EGFR or expression of a mutant form called EGFR variant III (EGFRvIII) is found in approximately 40-50% of all human gliomas." (PMID 29069805, 2017). "Four studies focused on the association between EGFR rs730437, rs1468727, rs11506105, rs845552, rs12718945, rs17172432, rs3752651, rs4947492 polymorphisms and glioma risk, among which two studies also reported the alleles and genotypes of EGFR rs9642393 in patients with glioma and controls." (PMID 29156842, 2017). "In addition, four GWAS and one nested case-control study were searched out and recruited in the pooled analysis of associations between EGFR rs11979158 and rs2252586 polymorphisms and glioma susceptibility." (PMID 29156842, 2017). "Single-nucleotide polymorphisms (SNPs) in EGFR gene are getting increasingly recognition of importance in the etiology, development and progression of glioma, as it has been verified in many studies that EGFR gene plays a key role in human tumors by regulating cellular processes." (PMID 29156842, 2017). "Therefore, the associations between EGFR gene polymorphisms and susceptibility to glioma in different ethnicities have been widely studies, aiming to find new insights into treatment with a target-oriented approach in glioma." (PMID 29156842, 2017). "The resistance of gliomas to this treatment approach might be due to the role of oncogenic mutations in genes that function up- and mid-stream of the EGFR/Akt pathway." (PMID 27733172, 2016). "Furthermore, nearly all subtypes of gliomas are associated with the amplification and overexpression of the epidermal growth factor receptor (EGFR) gene." (PMID 27733172, 2016). "Therefore, the present study was aimed to evaluate the effects of EGFR polymorphisms on the glioma patient prognosis." (PMID 27437777, 2016). "However, the exact pathogenesis and biological mechanisms by which polymorphisms in EGFR contribute to glioma development are unclear." (PMID 27437777, 2016). "Further, we studied if EGFR glioma risk variants were associated with EGFR and ErbB2 serum levels." (PMID 26906551, 2016). "To test this hypothesis, we screened and genotyped eight SNPs in EGFR and evaluated the associations between these SNPs and the prognosis of glioma patients in a Chinese population." (PMID 27437777, 2016). "siRNA against EGFR has caused up to 90% knockdown of EGFR mRNA in U251 glioma cells." (PMID 25688333, 2015). "Both deterioration and relapse of glioma are associated with EGFR mutations." (PMID 25950430, 2015). "In an attempt to increase the in vivo cell killing effect of PARP inhibition on glioma cells we ideated (given the up-regulation of pro-survival signalling pathways in PTEN-deficient glioma cells) the co-treatment with an inhibitor of EGFR to disable pro-survival signals." (PMID 25576921, 2015). "We previously reported that HDIs potentiate radiation-induced cell killing in a panel of human cancer cells through diverse mechanism: LBH589 preferentially radiosensitized human glioma cells that exhibited activated EGFR signaling due to the EGFRVIII mutation." (PMID 24418474, 2014). "Especially the EGF receptor (EGFR) is often overexpressed and mutated in gliomas." (PMID 25309325, 2014).